CD33 (CD33 molecule)
Diseases named in the same sentence as CD33 in open-access papers (continued):
Sharing a sentence is not in itself a finding about the gene and the disease.
tumor (continued). "Contrary, MDSCs were characterized by deficiency of MHC-II secretion and the existence of the myeloid marker CD33 in blood or CD11b in tumor tissue." (PMID 33204365, 2020). "METTL3 was located in the nuclei of tumour cells and tumour-infiltrating immune cells, while CD33+ cells were scattered mainly in the tumour stroma; isotype IgG was used as a control." (PMID 33059689, 2020). "HIF1-α, NF-κB and GM-CSF expression levels in tumour were higher, and CD33 + MDSCs showed an increased retention in the tumour stroma, whereas CD8 + lymphocyte numbers in tumour epithelium were markedly reduced after bevacizumab treatment." (PMID 31932754, 2020). "The number of MDSCs, defined as CD33+ cells, was significantly increased in tumor tissue compared to tumor-adjacent tissues." (PMID 32967190, 2020). "They observed an increased proportion of CD33+CD11b+HLA-DR− MDSCs in peripheral blood and tumor tissues which correlated with advanced disease stages and tumor lymph node metastases." (PMID 32849585, 2020). "Here, our data show that Gal-9 negatively regulates STING stability through protein-protein binding in both tumor cells and CD33+ cells." (PMID 32632113, 2020). "Four anti-CD33 Nbs showed fast and specific in vivo tumor targeting, with a rapid renal clearance of the excess labeled material." (PMID 31906437, 2020). "Increased CD33+S100a9+ staining positively correlated with higher tumour grade, differentiation and the presence of satellite lesions." (PMID 32747748, 2020). "Increased METTL3 levels and CD33+ MDSCs have been found in tumour microenvironments and lead to a poor prognosis." (PMID 33059689, 2020). "Other bispecific agents (LicMABs) have been produced by the binding domain of SIRPα to a tumor-targeting antibody such as anti-CD33 promoted elimination of AML tumor cells." (PMID 32677994, 2020). "We also demonstrated significant correlations with increased levels of these cytokines and CD33+S100a9+ cells in BTC tumours." (PMID 32747748, 2020). "Targeting antigens shared between AML blasts and suppressive immune cells such as CD33 and B7-H3 present the opportunity to modulate the microenvironment while targeting tumor cells." (PMID 32185132, 2020). "In this study, we focused on the distribution of METTL3 and CD33+ MDSCs in the tumour microenvironment of 197 patients with CC." (PMID 33059689, 2020). "Freshly obtained GC tumor tissue samples and peripheral blood were used for isolation of CD33+11b+HLADR- MDSCs cells from 40 GC patients and 31 corresponding controls using flow cytometry." (PMID 33247701, 2020). "Among all anti-CD33 Nbs, Nb_7 showed the highest tumor uptake (2.53 ± 0.69%IA/g), with low background signal, except in kidneys and bladder." (PMID 31906437, 2020). "We recently described a bi-specific TM that simultaneously targets CD123 and CD33 and that showed promising results in vitro and in vivo for anti-tumor efficacy." (PMID 32462078, 2020). "Not surprisingly, most pharma and biotech companies are pursuing hematological cancers by targeting lymphocyte restricted tumor-associated antigens such as CD19, CD20, BCMA, CD33, and CD123." (PMID 32351885, 2020). "The ex vivo biodistribution results confirmed the in vivo results, with a significant higher tumor targeting for anti-CD33 Nb_12, Nb_87, Nb_21, and Nb_7 compared to Nb_16 and to the non-targeting control 99mTc-ctrl_Nb." (PMID 31906437, 2020). "We found that tumour tissues displayed increased levels of METTL3 and CD33+ MDSCs compared with tumour-adjacent tissues from the same CC patients." (PMID 33059689, 2020). "The function, distribution and clinical relevance of the proportion of tumour-derived CD33+ MDSCs have been explored in recent years." (PMID 33059689, 2020). "Supported by pre-clinical data showing specificity and anti-tumor potency of dual CD33-CLL-1 CAR T cells, a first-in-human trial using these dual CAR T cells was conducted." (PMID 32435621, 2020).
tumor (continued). "Tipically, human tumor infiltrating MDSCs express the markers CD33 common to cells of myeloid lineage, but lack the expression of the maturation myeloid marker HLA-DR." (PMID 32849585, 2020). "Our data identified a positive association between METTL3 expression in tumour cells and in tumour-infiltrating immune cells and intratumoural CD33+ MDSC density." (PMID 33059689, 2020). "99mTc-Nb_21 also showed high tumor accumulation but also a high accumulation in liver and spleen, potentially due to the cross-reactivity with mouse CD33." (PMID 31906437, 2020). "CD33 is highly expressed on MDSCs in humans, especially M-MDSCs, but CD33 is a therapeutic target on circulating and tumor-infiltrating MDSCs across multiple cancer types." (PMID 32942545, 2020). "The significant positive correlation between IL-6 and GM-CSF with infiltration of CD33+S100a9+ cells indicates that these cytokines contribute to progression by modulating the immune composition of the tumour." (PMID 32747748, 2020). "BTC-derived factors promote suppressive myeloid cell expansion, and higher numbers of CD33+S100a9+ cells in resectable BTC tumours correlates with more aggressive disease." (PMID 32747748, 2020). "We further demonstrate the prognostic value of the combination of the METTL3 level in tumour-infiltrating immune cells and CD33+ MDSC density in CC patients, especially for those in advanced disease stages." (PMID 33059689, 2020). "T cells and CD33 + CD14+ tumour-polarised MDSCs were co-cultured at a ratio of 1:0.5 and compared to CD33 + CD14+ monocytes." (PMID 31462392, 2019). "Various tumor-derived factors have been reported to induce immature myeloid cells (CD33+ cells) to differentiate to MDSCs, these factors include prostaglandin E2, IL-6, IL-10, IL-1β, TGF-β, and proangiogenic factors such as vascular endothelial growth factor." (PMID 31620141, 2019). "Suppressive tumour polarised CD33+ cells down-regulated HLA-DR and upregulated CD68 consistent with a M1-like phenotype." (PMID 31462392, 2019). "Our previous findings have identified for the first time the clinical impact of tumor-infiltrating CD33+ MDSCs in high-grade serous EOC." (PMID 31001284, 2019). "Examination of 200 patient samples revealed significant infiltrations of CD33+ myeloid cells in the tumour stroma compared to healthy tissues (B and Supp 1A)." (PMID 31462392, 2019). "We observed more CD33 positive cells in the tumor stroma in the Inflamed A tumors while there were comparable amounts of intratumoral CD33 positive cells between Inflamed A and Inflamed B tumors." (PMID 31395880, 2019). "For example, when targeting CD33, which is abundantly expressed on healthy myeloid cells, even more “on target-off tumor” toxicity than with Blinatumomab is to be expected." (PMID 31142382, 2019). "After adjustment by TNM stage, four immune variables including the infiltration of CD8+/Foxp3+/CD33+ cells and the PD-L1 expression by tumor cells were selected to construct a prognostic nomogram." (PMID 30285868, 2018). "We detected the density and distribution of CD8+ T cells, CD4+ T cells, Foxp3+ T cells and CD33+ MDSC infiltrating the tumor site." (PMID 30285868, 2018). "We found a non-significant trend towards lower incidence of PD-L1 expression in both tumor and stromal compartments, as well as a decreased density of CD33+ cells in elderly patients." (PMID 30216999, 2018). "It has been shown that expression levels of CD33-related Siglecs are upregulated in tumor-infiltrating T cells in different human carcinomas and the upregulation of Siglec-14 on monocyte has been observed in SLE patients." (PMID 30294327, 2018). "Given that CAR33VH achieved similar anti-tumor efficacy as compared to My96CAR in vivo, but tended to produce less cytokines in response to CD33-positive tumor lines in vitro, it is possible that CAR33VH will have a lower risk of cytokine release syndrome." (PMID 30524966, 2018).
tumor (continued). "Our model utilizes four immune variables which are significantly associated with clinical outcomes for ESCC, including the infiltration of CD8+/Foxp3+/CD33+ cells and the expression of PD-L1 by tumor cells." (PMID 30285868, 2018). "In order to evaluate the in vivo anti-tumor activity of 123b-33bcCAR T-cells, we developed two mouse models with either luciferase-expressing MOLM13 (CD123+CD33+) or U937 (CD123−CD33+) cells to induce fluorescence visible tumor formation." (PMID 29515236, 2018). "In overnight cytokine release assays in which CAR T cells were challenged with the CD33+ tumor cells HL-60, MOLM-14 and KG-1a, CAR33VH elicited IFN-gamma, TNF-alpha and IL-2." (PMID 30524966, 2018). "In terms of clinical and pathological observations, we report a positive correlation between LMP1/GLUT1 expression in malignant cells and the abundance of CD33+ MDSCs in the NPC tumor microenvironment." (PMID 28732079, 2017). "Antibody-drug conjugated molecules targeting CD33, such as Gemtuzumab ozogamicin (GO) or SGN-CD33A have been developed to profit from CD33 internalization in order to deliver a drug into the tumor cell." (PMID 28061465, 2017). "Analysis of the luciferase activity of CD33+ tumor cells was performed for all mice in parallel for an overall time of 5 days." (PMID 28205621, 2017). "A high density of tumor-infiltrating CD33+ cells was also indicative of a poor prognosis, as shown in our previous study." (PMID 28732079, 2017). "Upon treatment with the CD16 × CD33 BiKE, NK cells from these patients produced IFNγ and TNFα, and lysed a CD33(+) AML tumor cell line as well as CD33(+) myeloid derived suppressor cells." (PMID 28157217, 2017). "Both tumor-infiltrating CD33+CD11b+HLA-DR−/lowCD14+ and CD33+CD11b+HLA-DR−/lowCD15+ cells expressed ARG1." (PMID 28008330, 2016). "iC9-CAR.CD33 ATCs, made them cytotoxic to CD33+ tumor cells, we investigated their function in an in vitro co-culture assay, and a luciferase-reporter cytotoxicity assay." (PMID 27907031, 2016). "As determined by the RNA-seq analysis, the overall expression of FLT-1 or sFLT-1 was similar in the CD33+ IMMCs from tumors and adjacent lung tissue, however the mFLT-1 was specifically upregulated in tumor IMMCs." (PMID 26046767, 2015). "We discovered that CRC patients had elevated levels of CD33+CD11b+HLA-DR− MDSCs in primary tumor tissues and in peripheral blood, and the elevated circulating MDSCs were correlated with advanced TNM stages and lymph node metastases." (PMID 25638150, 2015). "Significant reduction in tumor burden and a survival advantage was seen in mice injected with CD33 CAR vs. those injected with control T cells." (PMID 26484338, 2015). "Specific tumor killing of CD33+ AML cell lines was seen when co-cultured with CD33 CAR, and these cultures had higher levels of cytokines when compared to the cell lines co-cultured with control vector transduced T cells." (PMID 26484338, 2015). "What they found was that mice treated with CIK with either CD33 or CD123 bound CAR had significant reduction in tumor burden than those in the control group." (PMID 26484338, 2015). "Studies in cancer patients with different tumor types suggest various MDSCs definitions based, mainly, on the expression of CD33, CD11b, and CD15 molecules and by the absence or low levels of the HLA-DR molecule." (PMID 25436215, 2014). "Immunohistochemistry performed on tumors analyzed 48 hours after i.v. administration of EBV-CTLs seems to indicate that anti-CD33.CAR-EBV-CTLs were able to infiltrate the tumor." (PMID 22272203, 2012). "HNSCC tumor cell lines showed a high frequency of CD33+ MDSC induction and thus were good models for further studies of induction." (PMID 21658270, 2011). "Of note, some tumor models were found to induce both CD33+ and CD11b+ MDSC subsets, while others induced only one or neither population." (PMID 21658270, 2011).
tumor (continued). "Tumor-educated myeloid (CD33+) cells were then isolated, checked for viability, and tested for suppressive function by co-culture with fresh, autologous T cells in the presence of T cell stimuli." (PMID 21658270, 2011). "Additional clinical trials are required for validating the proposed use of CD33 antigen production rate, and initial tumor burden as biomarkers of the response to GO." (PMID 21915304, 2011). "Parameter sensitivity analysis showed that three parameters were critical determinants of I-AUC, namely drug efflux, CD33 antigen production rate, and initial tumor burden, all other parameters being much less influential." (PMID 21915304, 2011). "The results demonstrated high 6PGD expression in tumor-infiltrating CD33+CD14+ M-MDSCs." (PMID 41535266, 2026). "Thus, in vivo AML tumor cells were killed by CD33 | CD16b Tmod cells while the surrogate normal cells, differing only by their expression of CD16b, were protected." (PMID 40191207, 2025). "Similarly, Technetium-99m (99mTc)-labeled nanobody (Nb) has been evaluated in THP-1 tumor-bearing mice, providing a promising tool for CD33-targeted imaging." (PMID 40227793, 2025). "Similarly, aITGB2 expression remained high in the CD33/CD45-positive tumor population in spleen across all the cohorts." (PMID 41282197, 2025). "As observed in vitro, CD33 | CD16b Tmod cells killed the CD33(+)CD16b(-) tumor cells but not the CD33(+)CD16b(+) variant line in vivo." (PMID 40191207, 2025). "Whether the relatively high proportion of CD33+ myeloid cells observed may reflect a biologically relevant parallel to the myeloid-rich tumor microenvironment commonly seen in HNSCC is unclear, yet possible." (PMID 40508078, 2025). "The expression of CD33 on various hematopoietic precursor cells, such as myeloid progenitor cells, monocytes, macrophages, granulocytes, and dendritic cells (DCs), raises concerns regarding the potential for on-target off-tumor effects." (PMID 39893165, 2025). "Moreover, compared to KO HTM, abemaciclib-treated WT mice showed a significantly increased proportion of tumor-infiltrating CD33+ myeloid cells but with modest expression of the immunosuppressive ligand PD-L1." (PMID 39000582, 2024). "DARIC receptors incorporating the C2 epitope–specific VHH (DARIC-VHH1) displayed rapamycin-dependent recognition and activation against multiple gene-modified and AML cell lines, as well as an in vivo antitumor effect against established CD33+ human tumor xenografts in NSG mouse models." (PMID 38502193, 2024). "Tumor-associated microglia downregulated CX3CR1 but upregulated CD112, CD58 and CD33." (PMID 38123840, 2024). "In addition, B7-H4+ tumors in the isotype group have high expression of immunosuppressive genes including Tgfbr1 (TGFβ receptor), Cd33, and CD68 (tumor-associated macrophage markers)." (PMID 38687247, 2024). "As previously stated, IT applied to AML comprises checkpoint inhibitors (anti-PD-1, anti-PD-L1, anti-CTLA-4), T cells genetically redirected to leukemia cells (CAR-T therapies), antibodies against tumor antigens (GO, anti-CD33 antibodies), NK cell-based therapies, among others." (PMID 38400148, 2024). "Tumor cells upregulated Siglec ligands carrying sialic acid, which could interact with Siglec expressed on CD33-bearing cells, thereby suppressing immune cell activation." (PMID 38888513, 2024). "Considering that the intensity of antigen expression may also have an impact on inducing CAR downregulation, we sorted tumor cells with consistent levels of CD33, CD123 and CLL-1 antigen expression for co-culture with CAR T cells." (PMID 38184596, 2024). "Additionally, because of the drug’s consumption in the peripheral blood and its poor ability to enter the bone marrow tissues, high levels of CD33 tumor burden in the peripheral blood also confer resistance to the treatment and are linked to worse results." (PMID 38255313, 2024).
tumor (continued). "Since CD11b and CD66b were also found to be expressed on polymorphonuclear‐myeloid derived suppressive cells (PMN‐MDSC) which were described as a population of CD33+HLA‐DR− cells in the tumor microenvironment, we then introduced more markers to distinguish these cells with PMN‐MDSC." (PMID 38790136, 2024). "This anti-tumor efficacy was strictly dependent on the presence of CD33." (PMID 38473239, 2024). "In nodular KS, like in MCC, CD33+ PD-L1 positive cells have a peritumoral distribution and may function to protect the tumour from T lymphocyte infiltration." (PMID 37033972, 2023). "In another experiment from that same study, NSG-S mice that retained myeloid cells after receiving CD33 KO CD34+ cells and a CD33 directed CAR, experienced greater reduction in tumor burden and less toxicity compared to mice that loss myeloid cells after receiving control CD34+ cells." (PMID 36831198, 2023). "Bioinformatic analyses revealed five major cell types based on hallmark gene expression: myeloid (Cd11b; 12 clusters), lymphoid (Cd33/Ncr1/B220/Cd19; five clusters), tumor (Olig2/Cd276/Col11a1; one cluster), endothelial (Enpp2; one cluster), and fibroblast (plp1/Ptgds; one cluster) cells." (PMID 37971169, 2023). "By contrast, the CD33 directed CAR was able to target CD33+ tumor cells and normal myeloid cells." (PMID 36831198, 2023). "The leukemic cells of the other six PML::RARA-negative AML cases with APL-like morphological features, except the KMT2A-positive patient (due to the specific tumor biology), had more or less a typical myeloid immunophenotype, with strong expression of pan-myeloid antigens (CD33, CD13, MPO)." (PMID 36980947, 2023). "Furthermore, we examined the correlation between MDSC infiltration and PIK3CAmut, and found that the number of CD33+ MDSCs in situ was positively correlated with PIK3CAmut in tumours." (PMID 37965796, 2023). "First, to determine whether MIF from tumor cells or CD36+ CAFs mediates the regulation of CD33+ MDSC expansion, human or murine CD36+ CAFs were isolated from primary human HBV-related or murine HCC tumors." (PMID 36878933, 2023). "Bioinformatic analyses revealed five major cell types based on hallmark gene expression: myeloid (Cd11b; 12 clusters), lymphoid (Cd33/Ncr1/B220/Cd19; 5 clusters), tumor (Olig2/Cd276/Col11a1; 1 cluster), endothelial (Enpp2; 1 cluster) and fibroblast (plp1/Ptgds; 1 cluster) cells." (PMID 37333156, 2023). "Furthermore, curdlan also upregulated the expression of CD33, a marker of human MDSCs46, in both tumor and normal tissues, suggesting that Dectin-1 signaling also promotes human MDSC differentiation in CRCs." (PMID 36932082, 2023). "CD3 ScFvs as well as ScFvs specific for several tumor-associated cell surface antigens such as CD19, CD20, CD33, B-cell maturation antigen (BCMA), CD123, and CD38, as well as for tumor antigens identified in hematological malignancies, have been generated for clinical application." (PMID 36831533, 2023). "Therefore, targeting CD33+ MDSCs can effectively reduce the immunosuppression of MDSCs, slowing down tumor growth." (PMID 36131911, 2022). "Furthermore, knockdown of METTL3 potently reduces CD33+ CD11b+ HLA-DR− MDSCs and tumor-derived MDSCs in CD33+ or HeLa cells." (PMID 36071523, 2022). "Moreover, another study observed an increase in e-MDSCs (CD33+CD11b+HLA-DR–CD14–CD15–) in tumor tissues of CRC patients." (PMID 36081407, 2022). "CD33 CAR showed efficient anti-AML activity in vitro, different costimulators, different generation CAR structures, and PI3K inhibitors may affect the anti-tumor activity, proliferation, and persistence of CD33 CAR-T cells." (PMID 36523990, 2022). "Gemtuzumab ozogamicin (GO) is a CD33-targeted antibody–drug conjugate (ADC) linked to calicheamicin, that specifically targets the membrane antigen CD33 and releases a derivative of the cytotoxic calicheamicin component after internalization, leading to tumor cell death." (PMID 36163047, 2022).